STAT3 (signal transducer and activator of transcription 3)
Diseases named in the same sentence as STAT3 in open-access papers (continued):
Sharing a sentence is not in itself a finding about the gene and the disease.
cancer (continued). "STAT3 is well known to play both beneficial and pathogenic roles depending on its activation mode, that is tightly controlled as in physiological settings as opposed to aberrantly continuously active under pathological conditions such as chronic inflammation and cancer." (PMID 23460527, 2013). "STAT3 is a key downstream regulator of IL-6, playing an essential role in adaptive growth and cancer development in PC." (PMID 41596531, 2026). "PLK1 is a cell cycle regulator that is activated by NF-kB during cancer cell detachment and prevents β-catenin degradation and activates STAT3." (PMID 41596231, 2026). "Macrophage-derived IL-6 subsequently activates the JAK2/STAT3 pathway in cancer cells, suppressing ENZ-induced apoptosis and conferring therapeutic resistance." (PMID 41990247, 2026). "The review further highlights the strain-specific nature of detoxification, the impact of mycotoxin-induced dysbiosis on short-chain fatty acid production and inflammation, and the modulation of cancer-related pathways including NF-κB, STAT3, and IL-6." (PMID 41821854, 2026). "Some inhibitors targeting IL-6 or the JAK/STAT3 pathway have been tested and show promising results, including slowing or stopping cancer progression." (PMID 41596531, 2026). "CAIX helps cancer cells survive acidic stress by regulating intracellular and extracellular pH, a process enhanced by STAT3 signaling." (PMID 41596231, 2026). "STAT3 activation induces V-ATPase pump expression and activity, aiding cancer cells in managing intracellular pH and ROS levels, further promoting resistance to anoikis." (PMID 41596231, 2026). "This is an inhibitor evaluated in clinical trials for various cancers designed to suppress STAT3 activity by targeting its SH2 domain." (PMID 41596231, 2026). "SD-965 represents a promising STAT3 degrader for extensive evaluation for the treatment of human cancers and other human diseases." (PMID 41871272, 2026). "Signal transducer and activator of transcription 3 (STAT3) is a promising therapeutic target for human cancers and other human diseases." (PMID 41871272, 2026). "Ibuprofen reduces both the total STAT3 protein and its phosphorylated form (p-STATY705), particularly under hypoxic conditions in cancer cells, leading to decreased STAT3 activity." (PMID 41596231, 2026). "This interaction forms part of an autocrine loop where STAT3 and HIF1α mutually regulate each other to sustain cancer cell survival, growth, and adaptation under hypoxic stress." (PMID 41596231, 2026). "In PTEN-deficient cancer cells, inhibition of the PI3K/AKT pathway can lead to feedback activation of STAT3, which then limits the efficacy of PI3K-targeted therapies." (PMID 41596231, 2026). "It has been established that ZFAS1 interacts with STAT3, a widely recognized oncogenic transcription factor involved in the development and progression of cancer in TNBC cells." (PMID 41459628, 2026). "Adiponectin activates cellular functions and pathways via peroxisome proliferator‐activated receptor and AMPK that inhibit mTOR, PI3K, and STAT3 (the last via suppressing cytokine signaling 3), inhibiting cancer cell proliferation and progression." (PMID 41450167, 2026). "Inhibition of key pro-survival signaling pathways such as PI3K/AKT/mTOR and JAK2/STAT3 is significant for systematically dismantling the defense mechanisms of cancer cells, exhibiting extensive cross-talk with mechanisms discussed in other sections." (PMID 41599293, 2026). "A key finding of this study is that leptin drives EMT via STAT3 activation, a central event in cancer metastasis, evidenced by decreased E-cadherin levels and cytoskeletal alterations." (PMID 41562922, 2026). "Intracellular Brucella can escape host killing via inhibiting macrophages apoptosis and activated STAT3 can suppress apoptosis in cancer model." (PMID 41486271, 2026). "By reducing the constitutive activation of STAT3 and NF-κB in cancer cells, EGCG suppress VEGF production." (PMID 41608512, 2026).
cancer (continued). "Upon activation by ligands such as EGF, EGFR phosphorylates downstream effectors like STAT3, a transcription factor critical for cancer cell proliferation and survival." (PMID 41511366, 2026). "Studies have shown that IL-6 levels and the STAT3 signaling pathway are markedly increased in the skeletal muscle of cachexia mice induced by C26 cancer cells and that the inhibition of STAT3 alleviated muscle wasting." (PMID 41526343, 2026). "This overexpression of NCOA1 in MCF-7 cells resulted in heightened expression of Cyclin D1 and VEGF, two established target genes regulated by STAT3 in several cancer types." (PMID 41562922, 2026). "Versican (VCAN)-AS1 is an endogenous RNA that targets signal transducer and activator of STAT3 to inhibit miR-106a-5p and promotes the growth of cancer cells by blocking the STAT3/HIF-1α axis." (PMID 41614928, 2026). "The activation of and interaction between STAT3 and NF-κB are vital for regulating communication between cancer cells and inflammatory cells." (PMID 41596531, 2026). "Given the therapeutic effect of relevant ongoing clinical trials for STAT3 inhibitors in cancer treatment, the potential for STAT3-targeted interventions in precancerous diseases warrants further exploration." (PMID 41495021, 2026). "In this study, we identify c‐Met as a novel interactor for B7‐H3, revealing its role in promoting cancer cell stemness via the c‐Met/STAT3 signaling axis." (PMID 40859957, 2025). "Despite its potential as a therapeutic target in cancer, existing STAT3 inhibitors exhibit limited potency and provide only modest clinical benefits." (PMID 40166646, 2025). "Direct inhibition of STAT3 presents a promising therapeutic strategy, offering greater specificity and efficacy in preclinical models of cancer cachexia." (PMID 40704145, 2025). "Multiple studies have shown the crucial role of the JAK/STAT3 pathway in the efficiency of PD-L1 immune checkpoint inhibition in various human cancers." (PMID 41463161, 2025). "Studies have shown that fibroblast activation protein (FAP), a derivative of cancer-associated fibroblast-like cells (CAFLCs), can activate the JAK2/STAT3 signaling pathway in GC." (PMID 40485724, 2025). "The signal transducer and activator of transcription 3 (STAT3) plays a pivotal role in cell proliferation, angiogenesis, and immunosuppression, and its overactivation often leads to the development of cancer and poor clinical prognosis." (PMID 40078291, 2025). "Leptin stimulates cancer cell growth through JAK2/STAT3 and MAPK signaling, whereas adiponectin counteracts tumor progression by blocking the PI3K/AKT/mTOR pathway via AMPK activation." (PMID 40507982, 2025). "This review specifically focuses on five key signaling pathways: PI3K/Akt/mTOR, NF-κB, Wnt/β-catenin, MAPK/ERK, and STAT3, which play central roles in the mechanisms of cancer resistance." (PMID 40201307, 2025). "In the C26 mouse model of cancer cachexia, elevated levels of STAT3 and its activated form (pY705-STAT3) have been observed in white adipose tissue, implicating this pathway in adipocyte dysfunction and fat loss." (PMID 40704145, 2025). "This dynamic adaptability, often driven by intrinsic signaling pathways such as Notch, Wnt, MAPK, PI3K, and STAT3, allows subpopulations of cancer cells to evade therapy by transitioning into drug-tolerant or stem-like states." (PMID 41357203, 2025). "STAT3 involvement in cancer drug resistance is well known, including NB, JAK2/STAT3 signalling can be activated by a variety of RTKs, such as EGFR, MET, or AXL." (PMID 41511287, 2025). "This aligns with recent literature emphasizing the role of IL-6 in activating STAT3 signaling, which in turn drives oncogenic pathways, including proliferation, survival, and stemness of cancer cells." (PMID 40612845, 2025). "STAT3 is frequently found to be constitutively active in various cancer cells, including TNBC cells." (PMID 40918170, 2025).
cancer (continued). "Although STAT3 inhibits apoptosis in normal cells, it can stimulate angiogenesis and cell proliferation in cancer cells." (PMID 40061959, 2025). "Their interaction with epithelial and cancer cells triggers inflammatory cytokines (e.g., interleukins IL-6, IL-17, IL-8) and pathways (e.g., NF-kB, STAT3), promoting epithelial-to-mesenchymal transition, immune chemoattractants, and cancer cell proliferation." (PMID 40230461, 2025). "Addressing these challenges through advanced drug delivery systems, chemical modifications, and well‐designed clinical trials is crucial for harnessing the full potential of CUR and RES in targeting STAT3 for cancer therapy." (PMID 40860906, 2025). "USP5 stabilized STAT3 via its deubiquitination function, thereby enhancing the production of pro-angiogenic factors by cancer cells, including VEGF, ANGPT2, and CXCL1." (PMID 40691441, 2025). "Constitutive STAT3 activation is observed in many cancer types, including breast, prostate, lung, and hematological malignancies." (PMID 39786519, 2025). "Overall, understanding the intricate crosstalk between STAT3, Pol III activity, TP73, and miR-106a-5p provides valuable insights into the molecular mechanisms underlying cancer pathogenesis and unveils potential targets for precision medicine interventions." (PMID 40725945, 2025). "It has been reported that S100A4 activates STAT3 in cancer cells, while proteomics results showed that overexpression of RP11-54O7.17 decreased intracellular S100A4 content." (PMID 41173847, 2025). "Can inhibit JAK2/STAT3 pathway activation; regulate upstream and downstream indicators; suppress BC cell growth, proliferation, and migration; promote cancer cell apoptosis; and reduce inflammatory responses, thereby exerting anti-BC effects." (PMID 40351419, 2025). "Inhibiting CAF-cancer cell crosstalk using tocilizumab, a monoclonal antibody against the IL-6 receptor, can suppress STAT3 activation and restore gemcitabine sensitivity." (PMID 41425711, 2025). "This strategy will suggest a promising avenue for the development of targeted therapies against the critical functions of STAT3 in human cancers and potentially other diseases." (PMID 40118821, 2025). "These noncoding RNAs can either activate or inhibit STAT3 signaling, thereby influencing cancer cell behavior and treatment outcomes." (PMID 40860906, 2025). "PKM2 can also phosphorylate STAT3, strengthening the interaction between STAT3 and the Mek5 promoter, a critical gene involved in cell proliferation in cancer cells." (PMID 41032703, 2025). "We presented Atovaquone, a STAT3 inhibitor, as a therapeutic strategy to enhance the anti-cancer effect for Adriamycin-resistant TNBC." (PMID 40696387, 2025). "The STAT3 signaling axis represents a central regulatory node linking cancer development and inflammatory responses." (PMID 41597600, 2025). "OC downregulates the cancer‐linked genes, that is, MMP‐2, MMP‐9, Bcl‐xL, and Mcl‐1, inhibits the signal transducer and activator of transcription 3 (STAT3) phosphorylation and its initiation." (PMID 40979569, 2025). "Despite significant progress in elucidating the role of STAT3 in cancer cachexia, several key challenges remain that hinder the development of effective therapeutic strategies." (PMID 40704145, 2025). "We anticipate that these features will translate into a highly efficient inhibitory strategy against STAT3 in OC, warranting further studies in STAT3-dependent cancers." (PMID 41031165, 2025). "While JAK-mediated signaling can affect any of the STAT protein family members (STAT1, STAT2, STAT3, STAT4, STAT5α, STAT5β, or STAT6), STAT3 has been the most heavily implicated in oncogenesis and cancer progression." (PMID 40075607, 2025). "Whereas STAT3 is involved in regulating tissue maintenance, its remodelling, and immune response, and has a role in various cancer progression." (PMID 40895301, 2025).
cancer (continued). "Studies have shown that STAT3 is transiently activated in normal tissues to maintain normal cell biological functions, while its activation is continuous in CAFs and cancer cells." (PMID 40703348, 2025). "MUC2 downregulation leads to the activation of STAT3 and Chk2, suppression of CREB phosphorylation, and loss of E-cadherin, facilitating cancer progression and metastasis." (PMID 41378310, 2025). "STAT3 is constitutively activated in cancer cells and tumor microenvironment cells due to overactivation of cytokine and growth factor pathways, which is caused by receptor and non-receptor tyrosine kinase mutations and the defects of SOCS protein." (PMID 40078291, 2025). "This is achieved through the impairment of mitochondrial function and the inhibition of key signaling pathways, namely, Notch1 and JAK1/STAT3, which are critical drivers of cancer progression." (PMID 40019515, 2025). "The shared regulation of glucose and iron metabolic changes via STAT3, potentially also occurring in the EOMs, suggests preclinical testing of STAT3 inhibitors, currently being developed for cancer therapy." (PMID 40681476, 2025). "The JAK/STAT3 signaling pathway plays a critical role in cell proliferation, survival, and immune response regulation, making it a significant focus in cancer research." (PMID 40321161, 2025). "This drug targets STAT3, offering a new cancer therapy approach by disrupting signaling pathways that promote cancer cell growth, survival, and spread (Tošić and Frank 2021)." (PMID 40860906, 2025). "The existing scientific literature underscores the critical role of STAT3 in multiple human diseases, particularly cancer." (PMID 40166646, 2025). "EZH2 can physically interact with signal transducer and activator of transcription 3 (STAT3) and methylate STAT3 directly, promoting nuclear retention and increasing the activity of STAT3 and therefore exacerbating cancer." (PMID 40028035, 2025). "Targeting these regulators, either by directly inhibiting STAT3 or by disrupting the STAT3 signaling pathway, presents potential therapeutic strategies for cancer treatment." (PMID 40166646, 2025). "The STAT3 pathway interacts extensively with other signaling networks, and its role in cancer involves multiple downstream targets and feedback loops." (PMID 40860906, 2025). "Helicobacter induces epithelial gastric cells or cancer-derived cell lines to generate elevated levels of IL-8 via the activation of activator protein 1 (AP-1), NF-κB, or STAT3." (PMID 40264171, 2025). "The molecular docking analysis demonstrated that Melittin preferentially binds to key components of the JAK–STAT pathway, particularly JAK2 and JAK3, leading to the suppression of STAT3 activation and disruption of critical cancer-promoting pathways." (PMID 40243485, 2025). "Mechanistically, cancer-associated adipocytes (CAAs) secrete IL-6 and release free fatty acids (FFAs), which serve as metabolic sensors to activate ANGPTL4 via STAT3 and PPARα signaling pathways in TNBC cells." (PMID 40616161, 2025). "The JAK2/STAT3 signaling pathway, a member of the STAT family of transcription factors, is closely associated with the onset of various cancers and regulates cancer cell proliferation and migration." (PMID 40723784, 2025). "In tumors, STAT3 promotes the survival and drug resistance of cancer cells by inhibiting ferroptosis." (PMID 40371332, 2025). "Using computational docking tools, the study compares how well these natural products and standard cancer drugs bind to key proteins such as NF-κB, STAT3 and HIF-1α." (PMID 40507356, 2025). "These cytokines can activate oncogenic signaling pathways, including nuclear factor kappa-light-chain-enhancer of activated B cells (NF-κB) and STAT3, contributing to a pro-tumorigenic microenvironment and cancer progression." (PMID 41011846, 2025). "As IL-8 promotes cancer progression, it has been extensively investigated in this context and revealing interference with STAT3 signaling." (PMID 39985685, 2025).
cancer (continued). "A comprehensive, multi-targeted approach centered on STAT3 inhibition holds promise to transform cachexia management and improve quality of life in cancer patients." (PMID 40704145, 2025). "Persistent STAT3 activation contributes to oncogenic inflammation by counteracting anti-cancer Th1 immune responses induced by STAT1 and NF-κB." (PMID 40420174, 2025). "A recent study revealed that XIST activates the IL-6/STAT3 pathway to promote inflammation and cancer stem cell self-renewal." (PMID 40407589, 2025). "Signal transducer and activator of transcription 3 is a transcription factor that is essential for the survival and immune sequestration of cancer cells." (PMID 39792482, 2025). "STAT3’s involvement in cancer cachexia is primarily driven by its role in mediating inflammatory responses and its contribution to muscle wasting and dysregulated fat metabolism." (PMID 40704145, 2025). "TTI-101 is a first-in-class, orally delivered, small-molecule inhibitor of STAT3 that has been developed as a potential treatment for cancers." (PMID 39792482, 2025). "STAT3 activation stimulated by IL-6 and various cancers increases the expression of Atrogin-1 and MuRF-1, thereby enhancing the ubiquitin-proteasome system and contributing to muscle degradation." (PMID 40469669, 2025). "STAT3 is a transcription factor, which is frequently constitutively activated in cancer as in ABC DLBCLs, involved in many central oncogenic processes and its gene was also up-regulated in the CD79B-mutated group." (PMID 41295250, 2025). "Treatment with STAT3 inhibitors or knockdown of STAT3 inhibits metastasis in various cancers, including OSCC 49-51." (PMID 40027184, 2025). "STAT3 is well‐known for its activation in fibrosis and cancer, which usually occurs through JAK–STAT or TGF‐β/SMAD signalling pathways." (PMID 40464702, 2025). "These examples are far from exhaustive but illustrate the diverse functions that have made STAT3 a compelling target for cancer therapy and, as our data suggest, a target co-opted by E. chaffeensis." (PMID 41115066, 2025). "In cancer cells, these exosomes have been found enriched with certain biomolecules such as NF-κB, STAT3, and pro-inflammatory cytokines (e.g., TNF-α, IL-1β, and IL-6); this means cancer cell-derived exosomes recruit immune cells to target sites." (PMID 40443670, 2025). "Activated nuclear STAT3 has been identified in different cancers, including colon, breast, and HCC73–75." (PMID 41326479, 2025). "In ovarian cancer, the B7-H3 activation of JAK2/STAT3 was shown to inhibit apoptosis, promoting the proliferation, migration, and invasion of cancer cells." (PMID 40214484, 2025). "Activation of JAK/STAT3 signaling by executioner caspases has, to our knowledge, only been documented in cancer cells." (PMID 40875771, 2025). "The role of STAT3 in cancer has been assumed until now to be due commonly to the activation of gene expression in response to STAT3 dimers, formed through tyrosine phosphorylation in response to oncogenic tyrosine kinases such as steroid receptor coactivator." (PMID 40725945, 2025). "Considering the significant role of the STAT3 pathway in both fibrotic diseases and cancer metastasis during EMT,37, 38, 39, 40, 41, 42 we proceeded to explore the complex connection between NR2F1 and STAT3." (PMID 40641526, 2025). "Upon confirming the efficient cellular uptake of D11-PROTAC, its ability to degrade STAT3 protein in cancer cells was evaluated using HeLa and MCF-7 cells incubated with varying concentrations of D11-PROTAC." (PMID 40118821, 2025). "STAT3, a classical cancer marker and target, is overexpressed and constitutively activated in TNBC cells." (PMID 41173847, 2025). "Although both H2.1MS1KN and blended H2.1MS1:MS2KN spheres were effectively loaded with oligonucleotides, only H2.1MS1:MS2KN spheres delivered siRNA to HER2+ cancer cells that successfully silenced STAT3 expression." (PMID 40584785, 2025).